ICOS (inducible T cell costimulator)
Diseases named in the same sentence as ICOS in open-access papers (continued):
Sharing a sentence is not in itself a finding about the gene and the disease.
tumor (continued). "To this end, here we have identified the inducible co-stimulator (ICOS) as a pathway upregulated in NDV-infected tumours and investigated it as a target using recombinant NDV expressing the ICOS ligand (ICOSL) directly within the tumour microenvironment." (PMID 28194010, 2017). "In both treated tumours and the spleen, NDV-ICOSL/anti-CTLA-4 treatment resulted in the highest increase in the percentages of CD8+ cells characterized by high expression of Granzyme B and ICOS." (PMID 28194010, 2017). "The expression of membranous PD-L1 on tumor cells, CD3+ and CD8+ tumor infiltrating lymphocytes (TILs), co-stimulatory (CD137, GITR, ICOS), and co-inhibitory immune checkpoint molecules (PD-1, CTLA-4, TIM-3) were assessed semi-quantitatively using immunohistochemistry." (PMID 28771603, 2017). "Overall, the high ICOS+ Teff to ICOS+ Treg ratio induced by MVA-BN-HER2 alone or in combination with CTLA-4 blockade likely reflects a more effective immune response and correlated with strong anti-tumor efficacy." (PMID 26961085, 2016). "Our results revealed that treatment with CTLA-4 blockade augmented the number of ICOS+ CD4+ T cells but not ICOS+ CD8+ T cells in the tumor, blood, and spleen." (PMID 26961085, 2016). "Although the increase of ICOS indicated that circulating Tfh cells tended to be activated in the tumor environment in our study, the lack of changes in PD-1 expression suggested that Tfh cells were not fully activated actually." (PMID 26517519, 2015). "There were no changes in the proportion of activated (ICOS+) CD4 or CD8 T cells in the different surgical debulking groups either in the tumor itself or in the peripheral lymphoid organs (data not shown)." (PMID 25518732, 2014). "This thesis was further strengthened by Gobert's finding that only Treg cells located in these lymphoid aggregates actually expressed activation markers such as HCA-DR, GITR and ICOS, while FoxP3+Treg cells located within the tumor tissue itself did not." (PMID 25365237, 2014). "Surprisingly, in the ICOS stainings, few NLPHL and THRLCBL cases could be identified, with tumor cells expressing ICOS." (PMID 24244368, 2013). "CB-8F4CAR-iNK T cells had significantly elevated ICOS expression relative to AD-8F4CAR-iNK T cells, with distinct ICOS-enriched populations identified in clusters 5, 11, and 7 by UMAP dimensionality reduction, suggesting enhanced anti-tumor potential of the CB-CAR-iNK T cells." (PMID 40519924, 2025). "Focusing on T- cell and tumor cell states within different neighborhoods, in the Fibroblast-Enriched neighborhood, T- cells presented downregulation of activation markers, including CD44, CD45RO, HLA-A, ICOS, and Granzyme B, suggesting that fibroblasts play an immunosuppressive role." (PMID 41254766, 2025). "The high level of IL-1β induced by NB-PTX might be due to debulking in the absence of ICOS-Fc, which can modulate IL-1β production in the tumor microenvironment." (PMID 41471045, 2025). "Based on the fact that several tumor suppressive proteins (IDO1, VISTA, TIM-3, LAG-3 and ICOS) had a higher expression in the tumor-sparse region, we conclude that a wide range of T-cell suppressive features may hamper the expansion of T cells in regions also adjacent to the tumor." (PMID 39001353, 2024). "Analyses of Tregs in the HBV-associated HCC tumor microenvironment showed a more immunosuppressive and effective status, with increased expression levels of FOXP3, PD-1, CTLA-4, ICOS, and LAG-3 compared with non-HBV HCC." (PMID 38793588, 2024). "IHC was used to stain tumor tissues; however, because of the absence of some samples, ICOS levels were only determined in 47 patients, PD‐L1 levels were only measured in 62 patients, CD163 levels were only determined in 67 patients, and FOXP3 levels were only determined in 66 patients." (PMID 38616999, 2024).
tumor (continued). "Importantly, the Treg population in the tumor had, overall, a CD44hiCD62L– effector phenotype, but given the low levels of ICOS and CTLA-4 and the lack of proliferation, they clustered as cTregs." (PMID 38349740, 2024). "Therefore, ICOS signaling in HCC might both enhance and hamper local tumour control by liver-resident immune cells." (PMID 38440738, 2024). "Priming the tumour with the appropriate neoadjuvant chemoradiotherapy treatment could lead to higher immune infiltrations and higher expression of immune checkpoints, such as PD-1/PDL-1, CTLA4 or emerging new targets: LAG-3, TIM-3, TIGIT or ICOS." (PMID 38155973, 2023). "Polyamines may affect the expression of ICOS in Th1 cells through PD-1 and then regulate the immune function of Th1 cells, while PBT (polyamine Blocking Therapy) has been shown to enhance the anti-tumor effect of PD-1 blockade." (PMID 36119047, 2022). "However, there was a significant increase in ICOS expression on non-Treg CD4+ T cells in the tumor (62.16% vs. 34.04%, p = 0.004, n = 5/group)." (PMID 36056093, 2022). "Because the tumor microenvironment influences the TIL response, it will be important to further characterize the TILs for both antitumor and suppressive phenotypes and quantitate the ratios of activated CTLs (CD8+ICOS++) versus TRegs (CD4+FOXP3+) posttreatment." (PMID 35094188, 2022). "CARs are chimeric antigen-recognition receptors, consisting of an ectodomain, which binds a tumor specific cell surface receptor, and endodomains, consisting of CD3ζ as the signaling domain with co-stimulatory domains to provide robust activation (e.g. CD28, 4-1BB, or ICOS)." (PMID 35784326, 2022). "In the TDLN, in contrast to the tumor, we observed that a greater range of genes were regulated at day 2 following radiation therapy (160 genes) than at day 7 following radiation therapy (36 genes), and ICOS was not significantly changed." (PMID 36056093, 2022). "In addition to ICOS, ICOSL is also upregulated in the tumor following radiation therapy." (PMID 36056093, 2022). "One possible explanation for this disparity is that, in ICOSL-KO mice, the lack of endogenous ICOSL makes large amounts of OPN available to the tumor cells, an abundance that might promote metastasis of B16-ICOSL-high cells by overcoming the dominant negative effect exerted by ICOS." (PMID 35052731, 2021). "Additionally, we found that ICOS expression on Treg is downregulated after treatment with BLS, suggesting that the tumor resident Treg from treated mice may be less suppressive than infiltrating Treg in tumors from control mice." (PMID 34321536, 2021). "Thus, targeting ICOS on Tregs and interrupt the interaction between ICOS and ICOSL may be an effective measure for anti-tumor immunity." (PMID 34806028, 2021). "Moreover, in ICOS- or ICOS ligand (ICOSL)-deficient mice, the efficacy of anti–CTLA-4 therapy was significantly diminished, although the specific contribution of ICOS+CD4+ cells versus ICOS+CD8+ cells in tumor rejection was not addressed in this study." (PMID 33777008, 2021). "Moreover, the expression of immune checkpoints, such as CD137 (4-1BB), inducible co-stimulator (ICOS), T cell immunoglobulin and mucin domain 3 (TIM-3) changed in the tumor microenvironment could affect tumor progression." (PMID 34217372, 2021). "Moreover, (R)-crizotinib alone or with CDDP induced PD-1 expression on tumor-infiltrating CD4+ Foxp3− but not in CD4+Foxp3+ (Treg) cells bearing the exhaustion marker ICOS." (PMID 30940805, 2019). "Similarly, 7 days following radiation there was an increase in non-Treg CD4 cells expressing ICOS in the blood (7.73% vs 3.68%, p<0.0001, n=5/group) and the tumor (62.16% vs 34.04%, p=0.004, n=5/group)." (PMID 30400822, 2018). "In support of this hypothesis, phenotypic characterization of the tumour-infiltrating CD8+ cells from both treated and distant tumours revealed a more robust upregulation of the markers indicative of effector function (that is, ICOS and Granzyme B)." (PMID 28194010, 2017).
tumor (continued). "These clones were highly efficient in tumor killing, possessed polyfunctional activity, up-regulated inhibitory receptors, retained proliferative capability and activated an AKT pathway not-related to the differentiation phenotype and dependent on ICOS engagement." (PMID 27461275, 2016). "Therefore, ICOS expression was induced on CD4+ T cells by the presence of the tumor without any treatment." (PMID 26961085, 2016). "In patients with localized bladder cancer who were treated with preoperative ipilimumab, CD4+ T cells from the peripheral blood and tumor tissues were found to have increased expression of ICOS (inducible costimulator) compared to patients who did not receive ipilimumab." (PMID 24883190, 2014). "Finally, ICOS-Fc and PTX may also cooperate in modulating the immune components of the tumor microenvironment since treatment with the different drug formulations induced different changes in the cytokine expression pattern in the tumor mass." (PMID 41471045, 2025). "We analyzed the correlations between ICOS/ICOSL and prognosis and reached preliminary conclusions; ICOS expression may suggest slower tumor proliferation and better prognosis, which is different from existing research stating that ICOS is harmful to tumor immune in other cancer types." (PMID 37850501, 2023). "In addition to co-inhibitory immune checkpoint molecules, tumor-infiltrating Tregs also express TNFRs on the surface, such as glucocorticoid-induced TNFR-related protein (GITR), OX40, 4-1BB, inducible co-stimulator (ICOS), TNFR superfamily member 1B (TNFR2), and CD27." (PMID 37182149, 2023). "Furthermore, as for the promoting effects of IL‐17A on GC in our studies, IL‐17A induction may have negative impacts on anti‐tumor immune responses, and the impacts of B7‐H2 ligation to ICOS on Tregs in tumor immunosurveillance need further investigation." (PMID 34185422, 2021). "Of note, in the tumor site also CD137 and ICOS failed to provide functional advantage to CD28- T cells, nevertheless still sustained by CD11ahigh, although expressed only in a small fraction of the subset." (PMID 37898752, 2023). "This analysis showed that patients with positive (low or high) ICOS staining mainly had a smaller tumor size (≤3 cm) and longer OS than negative ICOS staining, whereas patients with negative or low ICOSL staining had a smaller tumor size (≤3 cm) and longer OS." (PMID 37850501, 2023). "In contrast to the findings in normal lung tissue from our NSCLC patients, when we examined tumor tissue in this cohort, ACE2 expression did not correlate with levels of PD-L1, ICOS, CTLA-4, PD-1, and TIGIT." (PMID 36324736, 2022). "Collectively, we found that PD-1, CTLA-4, VISTA, CD28, OX-40, 4-1BB, ICOS, and GITR were significantly increased in tumor tissues compared with non-tumor tissues." (PMID 33552954, 2020). "Expression of T-cell activation markers, CD69, ICOS and TIGIT, on tumor-infiltrating T-cells was not affected." (PMID 31747946, 2019). "In patients with primary UM, while circulating anti-tumor CD3–CD56dim NK cells and CD8+ and double-negative CD3+CD56+ NK-T cells decrease, pro-tumoral ICOS+CD4+FoxP3+ Treg cells increase, further supporting a role for Treg in tumor progression." (PMID 31750244, 2019). "The dual therapy reduces PD-L1+ cells and facilitates non-redundant tumour infiltration of effector CD8+, CD4+ T cells, with increased IFN-γ, ICOS, granzyme B and perforin expression." (PMID 28345650, 2017). "Tumor CD4+ T cell infiltration was not significantly altered by either gemcitabine or anti-CTLA-4, although ICOS expression as a marker of activation was decreased in all gemcitabine-treated mice, either with or without anti-CTLA4." (PMID 23626745, 2013). "Moreover, the absence of ICOS led to a significant reduction in anti-tumour T-cell responses triggered by the anti-CTLA-4 antibody, thereby hindering tumour rejection." (PMID 39325360, 2025).
tumor (continued). "Thus, our data are consistent with ICOS being an important target to identify both CD8 and non-Treg CD4 T cells with the potential to participate in tumor control." (PMID 36056093, 2022). "That prior study showed that expression of high levels of ICOSL promotes cell migration in response to OPN, which is inhibited by ICOS-mediated triggering of ICOSL, and that it inhibits tumor cell growth in anchorage-independent, but not in anchorage-dependent, conditions." (PMID 35052731, 2021). "With C57BL/6 mice it is not possible to model the net OPN/ICOSL interaction in the tumor context, since these mice fully express all three molecules (OPN, ICOS, and ICOSL) and thus the effect of each may be masked by an opposing action of the others." (PMID 35052731, 2021). "Therefore, although differences in ICOS expression on CD4+ T cells were observed, they were not alone characteristic of protective anti-tumor immune responses." (PMID 26961085, 2016). "This correlated with a pronounced increase in CD4+ICOS+ T cells in peripheral blood, as well as a clear increase in proliferating CD4+ T cells as determined by Ki-67 staining, although we did not detect this increase in the tumor as well." (PMID 23626745, 2013). "To highlight this different CD137 and ICOS related scenario found in the tumor with respect to the periphery, when CD28 is lacking, we cannot rule out that a fraction of intra-tumor PD1+CD28− T cells may have switched to a Treg-like phenotype, likely driven by the local milieu." (PMID 37898752, 2023).
cancer (141 papers, 2011 to 2026). A tumor composed of atypical neoplastic, often pleomorphic cells that invade other tissues. "The proportion of peripheral ICOS+CD4+ T cells is associated with irAE incidence in patients with cancer." (PMID 40198121, 2025). "Consistently, an enhanced EZH2-DPP4 axis and loss ICOS expression also indicated poor prognosis in these cancers." (PMID 40708008, 2025). "Consistent with the findings from the mouse model, ICOS upregulation in CD4+ T cells was associated with later irAE incidence in patients with cancer." (PMID 40198121, 2025). "PD-L1 protein was spatially clustered with CD80 and ICOS proteins, markers of activated T cells, and both were strongly associated with genes involved in cancer progression, immunosuppression, and chemoresistance such as CDYL25 and TBKBP126." (PMID 36575294, 2022). "Among all the significant associations, CD36 expression was positively correlated with CD27, CD28, CD40, and ICOS in multiple cancer types, but negatively associated with CD40 in TGCA." (PMID 34234847, 2021). "Among these single nucleotide polymorphisms (SNPs), ICOS rs10932029 T>C and rs4404254 T>C were most widely studied for their susceptibility to various cancers." (PMID 31235485, 2019). "Recently, several case–control studies have assessed the relationship of ICOS rs10932029 T>C polymorphism with cancer risk; however, the results are controversial." (PMID 31235485, 2019). "ICOS on T cells have been shown to have a crucial function in memory and effector T‐cell development, and interaction with its ligand is linked to the release of immunostimulatory and anti‐cancer cytokines." (PMID 36176603, 2022). "High ICOS was expressed in a minority of cancers (14%) and was most commonly seen in esophageal (24%) and pancreatic (22%) cancers." (PMID 40297627, 2025). "The ICOS–ICOSL (inducible T-cell costimulator–ICOS ligand) signaling pathway plays a significant role in regulating immune responses in cancers." (PMID 41180156, 2025). "Tregs suppress immune response in different types of cancer, and MCs interact with Inducible T-cell co-stimulator (ICOS)+ Tregs through IL-33 and IL-2 and promote cancer progression." (PMID 41425713, 2025). "Previous studies have highlighted the important role of the ICOS–ICOSL pathway in various cancers, including CCA." (PMID 41180156, 2025). "In the pan-cancer analysis of ICOS expression in this study, we also found that ICOS was expressed at lower levels in lung tissues." (PMID 38616999, 2024). "Noteworthy, this proangiogenic effect contrasts with that observed in tumors, where ICOS-Fc is primarily anti-angiogenic, suggesting that angiogenesis is driven by partly different mechanisms in wound healing compared to cancer development." (PMID 39596455, 2024). "Among the paired sample analyses that was performed with 11,123 samples in 23 cancers, ICOS mRNA expression was increased in BRCA, HNSC, KIRC, STAD (all p < 0.001) and ESCA (p < 0.05) and KIRP (p < 0.01)." (PMID 38616999, 2024). "This evidence suggests a strong need for an in-depth analysis of the ICOS+ T-cell context to successfully target the ICOS/ICOSL axis as a potential tool for cancer immunotherapy." (PMID 39684559, 2024). "Collectively, these data underscore the potential of ICOS as a pertinent target for cancer immunotherapies." (PMID 39201462, 2024). "As ICOS is expressed at high levels by Tregs in cancer, clinical trials are underway to elucidate the efficacy of agonistic anti-ICOS mAbs." (PMID 38891091, 2024). "In this study, we first performed a comprehensive pan-cancer analysis of ICOS followed by focused investigation to assess ICOS expression and clinical significance in NSCLC." (PMID 38616999, 2024). "At the pan-cancer level, the expression of ICOS in other types of cancer was more correlated with MSI / TMB." (PMID 36855091, 2023).